CRKL (CRK like proto-oncogene, adaptor protein)
Diseases named in the same sentence as CRKL in open-access papers (continued):
Sharing a sentence is not in itself a finding about the gene and the disease.
cancer (continued). "Analysis of the curated set of non-redundant studies in The Cancer Genome Atlas (TCGA) using the cBioPortal platform indicates that only 0.5% and 1% of cancer patients showed copy number increases for CRK and CRKL, respectively." (PMID 33801580, 2021). "Anaplastic lymphoma kinase (ALK) has been described in a range of human cancers and is involved in cancer initiation and progression via activating multiple signaling pathways, such as the PI3K-AKT, CRKL-C3G, MEKK2/3-MEK5-ERK5, JAK-STAT and MAPK signal pathways." (PMID 33391411, 2021). "Although these studies were instrumental in demonstrating the critical roles of Crk and CrkL in a variety of cancers, most examined either Crk or CrkL and failed to compare the roles of Crk and CrkL." (PMID 33801580, 2021). "While there are few reports about the effects of Crk and CrkL on cell proliferation in non-transformed cells, Crk and CrkL have been studied extensively for their effects in a number of cancer cell lines." (PMID 33801580, 2021). "The overexpression of CRKL is involved in EMT, invasion, and apoptosis in various cancers." (PMID 33094104, 2020). "The results showed that genes regulated by CRKL at the transcriptional level were not enriched in cancer related pathways." (PMID 31133010, 2019). "CRKL activates MAPK signaling as well as AKT signaling via PI3K, so we hypothesize that an effective approach against many cancers might be to use a combination of AKT and/or ERK inhibitors." (PMID 30653502, 2019). "Given that our studies only uncover CRKL is a critical transcriptional target of Hh‐GLI2 pathway in NSCLC cells, it will be interesting to test whether this transcriptional regulation also exists in other types of cancer." (PMID 34076957, 2021). "Since many of these studies addressed either Crk or CrkL, but not both, it is less clear whether the effects on cell proliferation are unique to one protein or shared by both proteins in a given cancer type." (PMID 33801580, 2021). "In addition, the complete blockage of cell migration and invasion in the absence of Crk and CrkL suggests that cancer cells depend entirely on Crk and CrkL for their motility." (PMID 33801580, 2021). "However, it was not clear whether the other protein between Crk and CrkL play similar roles because all the studies investigated effects by either Crk knockdown or CrkL knockdown in the given cancer cell type." (PMID 33801580, 2021). "Furthermore, we showed that Ova alone or by enhancing the therapeutic potential of Imatinib, reduced the viability of CML cell lines, dose-dependently, irrespective of the cancer stemness, as well as markedly inhibit the Bcr-Abl, p-CrkL, Stat5, and MDR protein expression levels in CD34+ cells." (PMID 29423045, 2018).
infection (6 papers, 2014 to 2023). The state of being infected such as from the introduction of a foreign agent such as serum, vaccine, antigenic substance or organism. "Co-transfection of a vector expressing CrkL tagged with eGFP recapitulated our results obtained by infection with recombinant IAV variants, showing a prominently nuclear green fluorescence that faithfully co-localized with wild-type NS1." (PMID 27092521, 2016). "Our research showed that CRKL expression had a significant rise at 24 and 48 h post-infection (p < 0.001)." (PMID 37376546, 2023). "EPEC infection induced a significant increase in CrkII-Tyr221 and CrkL-Tyr207 phosphorylation that peaked at 2 h of infection and decayed thereafter at an MOI of 45 while the levels peaked at 3 h at a lower MOI of 3 (data not shown)." (PMID 24675776, 2014). "Indeed, we found that EPEC induced progressive phosphorylation of CrkII-Tyr221 and CrkL-Tyr207 that peaked at 2 h of infection in our experimental conditions." (PMID 24675776, 2014). "When the kinetics of nuclear translocation of the Crk proteins was examined in more detail, we could observe first signs of nuclear accumulation of the Crk and CrkL at 6 h post-infection (p.i.)coinciding with the nuclei becoming clearly positive for NS1 staining." (PMID 27092521, 2016). "Nevertheless, within 2–3 days after infection, we noticed a striking induction of anchorage-independent growth, observed as cells overexpressing LZTR1 or CRKL formed three-dimensional clusters in 2D and 3D collagen cultures (top and bottom rows, respectively)." (PMID 35197475, 2022). "In summary, TepP is a C. trachomatis T3S effector recruiting CRK and CRKL adaptor proteins, as well as PI3K, to modulate innate immune signalling early in host cell infection that is likely required for chlamydial growth." (PMID 31528632, 2019). "Based on TepP’s ability to stably recruit PI3K, CrkL, and CrkI/II proteins and on the role that Crk proteins play as adaptors linking receptors to signaling outputs, we hypothesize that TepP acts as a scaffold for the localized reprogramming of signaling proteins early during infection." (PMID 28744480, 2017). "Secretion: T3S; targets: CRK, CRKL, PI3K subunits, and GSK3B; localization: cytosol, near the early vacuole; function: modulation of host gene expression related with immune signalling in early stages of infection." (PMID 31528632, 2019). "CrkL and PI3K copurify with TepP translocated during infection." (PMID 28744480, 2017). "CrkL, GSK, and both PI3K subunits (p110 and p85) coprecipitated with TepP during infection." (PMID 28744480, 2017).
bacterial infection (1 paper, 2009). "Indeed, tyrosine phosphorylation of Crk (Y221) by Shigella infection and to a lower extent, phosphorylation of CrkL by PDGF was decreased in Unc119 overexpressing cells at 15 and 30 min after bacterial infection." (PMID 19381274, 2009).
renal disease (1 paper, 2020). "However, additional studies revealed that a major driver of renal disease in DGS1 is CRK-like proto-oncogene, adaptor protein (CRKL), mutations of which sensitise the genetic background and modify the penetrance of congenital kidney and urinary tract anomalies in DGS1 patients." (PMID 32348957, 2020).
CRKL also shares sentences with these, for which no sentence is quoted: non-small cell lung carcinoma (4 papers); neuroblastoma (3); small cell lung carcinoma (3); autism spectrum disorder (2); congenital heart disease (2); developmental delay (2); glioma (2); oral squamous cell carcinoma (2); renal cell carcinoma (2); acute lymphoblastic leukemia (1); adenocarcinoma (1); anorexia nervosa (1); atrial septal defect (1); atrioventricular septal defect (1); bulimia nervosa (1); cervical (1); choroideremia (1); cutaneous melanoma (1); cystic teratoma (1); ductal carcinoma (1); esophageal carcinomas (1); fibrosarcoma (1); gynecological cancer (1); hypospadias (1); laryngeal squamous cell carcinoma (1); Leber congenital amaurosis (1); lung squamous cell carcinomas (1); lupus (1); Mitral regurgitation (1); myeloma (1).
A further 11 diseases each share a sentence with CRKL in 1 paper.